EIF4E (eukaryotic translation initiation factor 4E)
Diseases named in the same sentence as EIF4E in open-access papers (continued):
Sharing a sentence is not in itself a finding about the gene and the disease.
viral infection (continued). "Notably, eIF4E and its isoform eIF(iso)4E are pivotal for viral infection and act as recessive resistance genes against various potyviruses in a wide range of plants." (PMID 32849681, 2020). "We also obtained further insight into the seemingly paradoxical observations that viral infection results in a reduction of the available pool of eIF4E –the rate limiting factor for translation initiation–yet viral mRNAs contain a cap structure that is indistinct to that of host mRNAs." (PMID 31226162, 2019). "We further explored whether the inhibitory effect of HHT on viral infections is related to the phosphorylation of eIF4E." (PMID 30388805, 2018). "Indeed, during viral infection, translation of cellular mRNAs is reduced due to the sequestration of eIF4E by 4E-BP induced by Vpr, which renders eIF4E unavailable." (PMID 30597859, 2018). "The compatible interaction between eIF4E and VPg is a prerequisite for successful virus infection." (PMID 28771520, 2017). "Several viral infections induce an accumulation of phosphorylated eIF4E that correlates with the inhibition of cellular protein synthesis, whereas other infections can lead to eIF4E dephosphorylation." (PMID 25561727, 2015). "Moreover, a recent study demonstrated that p-eIF4E regulates interferon production by controlling the translation of Nfkbia mRNA, thereby modulating sensitivity to viral infections." (PMID 25561727, 2015). "In addition to this traditional function, many studies have demonstrated that eIF4E and its isoform, eIF(iso)4E, often participate in the virus infection of plants." (PMID 23505421, 2013). "Hence, inactivating eIF4E proteins in various plants may prevent the virus from using the host cellular machinery, resulting in genetic resistance to viral infections." (PMID 39519021, 2024). "However, the precise roles of eIF4E during virus infection have yet to be demonstrated." (PMID 27746794, 2016). "To test this hypothesis and because previous results have shown that physical interaction between eIF4E and VPg is necessary for viral infection, we performed yeast two-hybrid interaction assays between the three eIF4E proteins from susceptible tomato lines and a selected set of VPg proteins." (PMID 22242134, 2011). "Furthermore, the loss of eIF4E phosphorylation in cells expressing the eIF4E mutant S209A is associated with impaired translation of the Nfkbia mRNA, which encodes the NF-κB inhibitor IκBα; this leads to an enhanced type I IFN response that protects against viral infection." (PMID 25561727, 2015). "Cleavage of eIF4G during apoptosis or viral infection separates the binding domain for PABP and the mRNA cap binding protein, eIF4E, from the domains that bind eIF4A and allow ribosome attachment (referred to as the middle fragment of eIF4G or M-FAG)." (PMID 15507151, 2004). "In some plants, an eIF(iso)4E gene rather than an eIF4E gene contributes to defense responses to certain viral infections." (PMID 39519021, 2024). "These capped mRNAs do not rely on EIF4E and are translated under various cellular conditions, including where EIF4E activity is compromised, such as during cellular stress states, viral infections, and in diseases like cancer." (PMID 38535990, 2024). "Previous studies have shown that during some viral infections—for example, Encephalomyocarditis virus (EMCV) or VSV—the formation of the eIF4F complex is prevented through the conformational changes in eIF4E via binding of the 4E-binding protein 1 (4E-BP1), leading to the translation inhibition." (PMID 30700020, 2019). "In the case of potyviruses, the host eIF4E has been shown to affect virus infection, but there is no direct evidence that shows eIF4E function in virus multiplication at the intracellular level." (PMID 27746794, 2016).
viral infection (continued). "The absence of eIF4E‐1 or the failure of its truncated form to bind the viral VPg, a step that appears to be necessary although not sufficient to establish viral infection, could represent the key element in the va‐mediated resistance." (PMID 31115167, 2019). "In mammals, translational stimulation by growth factors, nutrients, or serum is correlated with increased eIF4E phosphorylation, whereas eIF4E dephosphorylation is correlated with the inhibition of cap-dependent translation under heat-shock conditions, lack of nutrients, or some viral infections." (PMID 25690796, 2015). "However, the effect of miR-141 on virus infection was not known, except one recent report showing that enterovirus can induce miR-141 and contribute to the shutoff of host protein translation by targeting the translation initiation factor eIF4E." (PMID 23663545, 2013).
prostate carcinoma (43 papers, 2009 to 2026). A carcinoma that arises from epithelial cells of the prostate gland. "Substantial evidence suggests that dysregulated expression of EIF4E is associated with 30% of human tumors, including head and neck cancer, endometrial cancer and prostate cancer." (PMID 36544768, 2022). "Thus, in this work we aimed at i) identifying the interaction site of the Hsp27/eIF4E complex and ii) interfere with the relevant protein/protein association mechanism involved in castration-resistant progression of prostate cancer." (PMID 29100389, 2017). "Although the effect of eIF4E phosphorylation on its affinity for the cap remains the subject of research, phosphorylation of serine 209 has been linked with cell survival and proliferation in a number of cancers, including prostate cancer." (PMID 25561727, 2015). "We demonstrate that the eukaryotic initiation factor 4E (eIF4E) cap-binding domain is a critical regulator of lineage plasticity in prostate cancer." (PMID 41984598, 2026). "These discoveries uncover a role for the eIF4E cap-binding domain in lineage plasticity and highlight that targeting this domain offers a promising strategy to overcome treatment resistance in prostate cancer." (PMID 41984598, 2026). "Specifically, AT-I was shown to overcome eIF4E-mediated resistance in prostate cancer by inhibiting the Hsp27/eIF4E pathway, thereby enhancing the chemosensitizing effects of cabozantinib." (PMID 41599296, 2026). "For instance, eIF4E-driven selective translation of Hgf, Spp1 and Bgn suppresses immunotherapy by recruiting MDSCs in prostate cancer, while eIF2α phosphorylation-mediated integrated stress response (ISR) underlies sorafenib resistance of HCC." (PMID 41144132, 2025). "Dysregulation of eIF4E has been shown to affect proliferation, invasion, migration, and chemotherapy resistance in prostate cancer." (PMID 40809690, 2025). "The role of eIF4E in prostate cancer is influenced by factors such as phosphorylation modification and miRNA." (PMID 40809690, 2025). "Mechanistically, eIF4E facilitates m7G modification of specific mRNA 5′end structures, impacting key pathways in prostate cancer development like PI3K/Akt/mTOR and Ras/MAPK, ultimately regulating the progression of prostate tumors." (PMID 40809690, 2025). "Previous studies showed that miR-455-3p, miR-15a and miR-141 mediated direct repression of eIF4E and suggested the tumour suppressing role of miRNAs in prostate cancer, renal cell carcinoma, and non-small cell lung cancer, respectively." (PMID 38378793, 2024). "Earlier, we had reported the potential of VNPP433-3β in treating preclinical models of castration-resistant prostate cancer by promoting degradation of f-AR and preventing phosphorylation of eIF4E by depleting Mnk1/2." (PMID 36831540, 2023). "Phosphorylation of eIF4E by MNKs supports protein synthesis, cell cycle progression, and proliferation in prostate cancer cells." (PMID 36814956, 2023). "Further analysis of GO and KEGG functional enrichment analysis of prostate cancer after overexpression of EIF4E." (PMID 36686743, 2022). "We used The Human Protein Atlas database to analyze the changes of eIF4E Immunohistochemical in human prostate cancer tissues." (PMID 36686743, 2022). "Phenazine derivative compound #14 was demonstrated to specifically disrupt Hsp27/eIF4E interaction and significantly delay castration-resistant tumor progression in prostate cancer xenografts." (PMID 33925528, 2021). "Other groups also completed early stage clinical trials targeting eIF4E with ribavirin, e.g., castration-resistant prostate cancer and head and neck cancers, and observed objective clinical responses." (PMID 33375634, 2020). "In mouse models, eIF4E was targeted with an antisense oligonucleotide (ASO) with promising results in a prostate cancer mouse model." (PMID 33375634, 2020).
prostate carcinoma (continued). "Here, we first explored the inhibitory effect of these two new analogs on Mnk1/2, eIF4E peIF4E and some downstream targets in four prostate cancer cell lines." (PMID 31653008, 2019). "Our findings provide the first preclinical evidence that simultaneous inhibition of AR and eIF4E activation is a novel and efficacious therapeutic approach for PCa, and that NRs hold significant promise for treatment of advanced prostate cancer." (PMID 25605250, 2015). "In summary, our study identifies for the first time novel retinamides that can simultaneously inhibit both AR signaling and MNK mediated eIF4E activation in prostate cancer cells." (PMID 25605250, 2015). "HSP27 has been shown to have strong anti-apoptotic properties through stabilization of the protein translation factor eIF4E in resistant prostate cancer cells." (PMID 25544765, 2015). "Androgen receptor (AR) and MNK activated eIF4E signaling promotes the development and progression of prostate cancer (PCa)." (PMID 25605250, 2015). "It should be noted that another recent study employed a mass spectrometric approach and found that rapamycin alters phosphorylation of Mnk2 on Ser-437 in prostate cancer cells, triggering Mnk2 activation and eIF4E phosphorylation independently of MAPKs." (PMID 25193863, 2014). "For example, eIF3h and eIF4E are frequently overexpressed in advanced prostate cancers, together with increased phosphorylation of eIF4E and eIF4E-BP1, which support increased translation." (PMID 23405127, 2013). "Studies in human leukemia specimens, and later in a mouse model of prostate cancer, strongly suggest that cells with elevated eIF4E develop an oncogene dependency to it, making them more sensitive to targeting eIF4E than normal cells." (PMID 20049173, 2009). "In prostate cancer cells, Hsp27 inhibits apoptosis through its regulatory effect on eIF4E." (PMID 36686743, 2022). "ATL-1 can inhibit the malignant evolution of prostate cancer cells by inhibiting Hsp27/eIF4E." (PMID 36686743, 2022). "The results showed that eIF4E was highly expressed in human prostate cancer tumor tissues." (PMID 36686743, 2022). "In prostate cancer, eIF4E levels were also correlated with worse prognosis." (PMID 20049173, 2009). "Furthermore, prostate cancer drug resistance was enhanced after upregulation of EIF4E." (PMID 36686743, 2022). "Moreover, Hsp27 seems to have a cytoprotective role in the castrate-resistant prostate cancer cell line (LNCaP) by directly chaperoning the eukaryotic translation initiation factor 4E (eIF4E) and protecting it by ubiquitination, consequently promoting cell growth and survival." (PMID 35453647, 2022). "In GO enrichment analysis for up regulated genes, genes such as EIF4E and RPS24 were associated with cancer cell proliferation in many cancer types such as prostate cancer and colorectal cancer cells, but these genes may be responsible for the proliferation of GBM cells." (PMID 31137733, 2019). "Moreover, the analysis suggested that direct targeting of the translational machinery, specifically eIF4E, could be efficacious in androgen-independent prostate cancers." (PMID 20126616, 2010). "The study indicated that two major pathways involved in prostate cancer progression, PI3K/Akt/mTOR, and Ras/MAPK, intersect at the eukaryotic transcription initiation factor eIF4E." (PMID 35982949, 2022). "Since AR plays a pivotal role in prostate cancer and MNK/eIF4E pathway is involved in cancer resistance and progression, dual AR/MNK inhibition seems to be a promising PCa therapy." (PMID 32340135, 2020). "Our group recently discovered a class of novel retinamides (NRs; semi-synthetic natural products), small molecule Mnk1/2 protein degraders that potently inhibit Mnk-eIF4E and mTORC1/4E-BP1/p70SK6 oncogenic signaling in breast and prostate cancer models." (PMID 30832411, 2019).
prostate carcinoma (continued). "Therefore, in the molecular diagnosis of prostate cancer, we can also introduce changes in the levels of c-Myc, eIF4E and CDK4 to evaluate the progression of prostate cancer." (PMID 34863188, 2021). "Although there is no direct evidence for MNKs overexpression in prostate cancer patient samples, a few studies have shown that elevated eIF4E levels and hyperphosphorylation, which reflect high MNKs activity, were correlated with disease progression." (PMID 32340135, 2020).
melanoma (40 papers, 2002 to 2025). A malignant, usually aggressive tumor composed of atypical, neoplastic melanocytes. "This indicated that, despite the oncogenic mutations in the ERK pathway in melanoma cells, there is still spare capacity for further increase of eIF4E phosphorylation." (PMID 39436655, 2024). "In support of the immune suppressive cytokine signature associated with phosphorylated eIF4E expression, eIF4EWT melanomas showed a significant increase in MDSCs and fewer cytotoxic CD8+ T-cells, compared to melanomas with phosphorylation-deficient eIF4E." (PMID 32731503, 2020). "Here, our results showed that the phosphorylation level of eIF4E was associated with CXCR7 expression in melanoma cells." (PMID 30804329, 2019). "In melanoma patients, eIF4E phosphorylation is known to be elevated and associated with poorer prognosis." (PMID 30804329, 2019). "Aberrant activation of eIF4E has been linked to resistance to therapy and poor outcome in breast, melanoma, prostate, and gastric cancers." (PMID 28417568, 2017). "Further evidence supporting a link between NGFR and innate immunity comes from a recent melanoma study wherein tumors deficient in phospho-eIF4E, a translation initiation factor regulating, among others, NGFR, showed increased infiltration of tumor-promoting myeloid-derived suppressor cells." (PMID 36638181, 2023). "Additionally, previous reports showed that both eIF4E and eIF2α are also closely associated with melanoma." (PMID 35707354, 2022). "Increased levels of eIF4E are associated with poor prognosis in many cancer types including breast, melanoma, prostate, gallbladder, colorectal adenocarcinoma, and hepatocellular carcinoma and correlate with advancing tumor grade in squamous cell carcinoma and esophageal cancer." (PMID 32517051, 2020). "Given recent reports that phospho-eIF4E promotes immunosuppression in melanoma by regulating cytokine translation, we also observed SENP3-RACK1-eIF4E axis was existed in hepa cells." (PMID 39755756, 2025). "Inhibition of phosphorylated protein eIF4E (phospho-elF4E) has shown inhibition of MDSCs and their immunosuppressive effects, a potential future immunotherapy target for the treatment of melanoma progression." (PMID 40872475, 2025). "Common BRAFV600E mutation in melanoma results in hyper-activation of the MAPK/ERK pathways, which correlates with MNKs-associated increase of phosphorylation of eIF4E, and favors tumorigenesis." (PMID 33916175, 2021). "MNK1/2 inhibitors, which block eIF4E phosphorylation, decreased melanoma cell invasion, restored MITF expression and repressed NGFR expression in BRAFi-resistant cells, and cooperatively inhibited their growth in combination with vemurafenib." (PMID 34604096, 2021). "Inhibition of MEK1 leads to a further increase the number of inhibitory complex eIF4E-4EBP1 in melanoma cells, which is consistent with our previous report." (PMID 34223196, 2021). "Combining MAPK inhibitors with an eIF4A inhibitor or with an inhibitor blocking the eIF4E-eIF4G interaction synergistically inhibited melanoma growth." (PMID 34604096, 2021). "We quantified the absolute number of eIF4E-4EBP1 complex in melanoma cell lines upon treatment with a MEK1 inhibitor (cobimetinib)." (PMID 34223196, 2021). "In patient-derived melanoma samples, increased nuclear and cytoplasmic levels of total and phosphorylated eIF4E has been observed, and high levels of phosphorylated eIF4E were correlated with poor prognosis." (PMID 32517051, 2020). "Our group has shown that MNK1/2 inhibition using SEL201 blocks the progression of metastatic KIT melanoma, concomitant with suppression of eIF4E phosphorylation." (PMID 32517051, 2020). "Here we found that the MNK1/2 inhibitor cercosporamide diminished CoCl2-induced HIF-1α accumulation in melanoma cells, indicating that eIF4E phosphorylation is required for CXCR7-facilitated translation of HIF-1α." (PMID 30804329, 2019).